CD24 (CD24 molecule)
Diseases named in the same sentence as CD24 in open-access papers (continued):
Sharing a sentence is not in itself a finding about the gene and the disease.
breast cancer (continued). "Among tested breast cancer cell lines, paclitaxel-induced increases of Snail were the highest in MDA-MB-231 and Hs578T cells, which are highly invasive breast cancer cell lines, associated with cancer stem-like features (CD44+/CD24−)." (PMID 26462028, 2015). "CD24 expression was more frequently found in HER2-positive breast cancer (34.2%) than in HER2-negative breast cancer (26.4%) (P = 0.047)." (PMID 26444008, 2015). "In accordance with this finding, CD24 was revealed to be involved in the regulation of stemness and the epithelial to mesenchymal transition in breast cancer cells." (PMID 26444008, 2015). "Although the clinical significance and function of CD24 in various cancers including breast cancer have been frequently reported, little is known concerning the regulatory mechanism of CD24." (PMID 26444008, 2015). "The percentage of CD44+CD24− cells within breast cancer cell lines was found to be uncorrelated with tumorigenicity." (PMID 25905435, 2015). "In conclusion, our study indicates that in combination, EGFR and CD44/CD24 expression status are powerful identifiers of breast cancer patient subgroups with different clinical behavior." (PMID 25429827, 2015). "It has been demonstrated that a small number of breast cancer cells with the CD44+/CD24- phenotype can form tumors after orthotopic injection into the mammary fat pad in immunocompromised mice." (PMID 26528725, 2015). "Recent breast cancer studies have shown that DACH1 can directly influence the gene expression of stem cells, causing them to under-express CD24." (PMID 24392136, 2014). "In this study, we characterized CD44+CD24- breast CSC from a human breast cancer cell line, BT-20 cells, and found that CSC had potent capacity to form mammospheres in vitro and solid tumors in SCID mice, consistent with previous studies." (PMID 25301732, 2014). "Cancer stem/progenitor cell populations have been isolated in clinical samples of breast cancer tissue that characteristically show a CD44+/CD24–/lin− phenotype and also preferentially express other stem cell markers such as nucleostemin and active ALDH-1." (PMID 25209720, 2014). "Breast cancer stem cells (CSCs) isolated from the tumors were determined by flow cytometry analysis using CD44+/CD24- or low." (PMID 24914410, 2014). "To obtain breast CSCs, we have stained and sorted both NIPBC-1 and NIPBC-2 cell lines using antibodies against CD44 and CD24 cell surface markers taking MCF7 breast cancer cell line as positive control." (PMID 24502646, 2014). "We then classified all samples according to a GES of breast cancer stem cells (CD44+/CD24-/low-mammospheres-forming cells)." (PMID 25277734, 2014). "Clarke and colleagues isolated TICs from metastatic human breast cancers based on their specific CD44+/CD24-/low/ESA+ antigenic phenotype." (PMID 25216750, 2014). "Characterization of CD44+CD24-Cancer stem cell(CSC) derived from breast cancer cells indicated that CSC rapidly formed mammospheres and had potent tumorigenicity in vivo." (PMID 25301732, 2014). "The same group later showed a similar genetic diversity between CD44+ and CD24+ cell populations for a subset of genetic markers commonly altered in breast cancer." (PMID 24998755, 2014). "The EMT signatures included a signature seen in CD44(hi)/CD24(lo/-) enriched breast cancer stem cells and an EMT core signature produced by overexpression of Twist, Snail, Gsc and TGF-β1." (PMID 25519510, 2014). "CD44+/CD24- have been identified as cancer stem cell markers for breast cancer, CD133+ aimed at brain tumors and colon cancer, as well as CD20 designed for melanoma." (PMID 24670249, 2014). "CD44+/CD24-/low is considered to be the biomarker for the tumor stem/progenitor cell phenotype in breast cancers." (PMID 25213022, 2014).
breast cancer (continued). "Shipitsin and colleagues performed copy number analysis using DNA microarrays of CD44+ versus CD24+ cell populations from a single breast cancer patient and showed that both populations shared copy number alterations, indicating a clonal origin." (PMID 24998755, 2014). "Both NIPBC-1 and NIPBC-2 cell lines showed the presence of 0.2% and 0.1% of CD44+/CD24- breast cancer stem cells respectively which is relatively similar to the commercially available breast cancer cell line." (PMID 24502646, 2014). "Breast cancer is the first human carcinoma in which a subpopulation of cells displaying a specific CD44+/CD24-/low/ESA+ antigenic phenotype was found to have TIC properties." (PMID 25216750, 2014). "For example, CD44+CD24−/low population is tumorigenic with stem cell properties in breast cancer, but CD24+ cells were dramatically enriched in distant metastases in breast cancer patients." (PMID 25237769, 2014). "The most widely accepted markers to identify mammary cancer stem cells are the expression of CD44/CD24 and ALDH." (PMID 24498388, 2014). "Previous study indicated that autophagy positively regulates the CD44+CD24-/low breast cancer stem-like phenotype; however in the present study our data showed that resveratrol-induced autophagy plays a negative mechanism for BCSCs maintenance." (PMID 25068516, 2014). "Fresh tumor material from five randomly chosen breast cancer patients was disaggregated and triple stained with anti-EpCAM, anti-CD24 and anti-SSEA-4 antibodies." (PMID 25419568, 2014). "In another study using mammospheres, CSCs in canine mammary neoplasms exhibited a CD44+/CD24- phenotype in four different tumoral cell lines." (PMID 24119896, 2013). "Surface CD44 and CD24 expression were assayed in established breast cancer lines and in seven patient-derived TNBC dissociated tumour cultures (DTs)." (PMID 23982961, 2013). "In human cases, however, Giatromanolaki and colleagues found that breast cancer patients that present with CD44-/CD24- cells had a worsened overall survival." (PMID 23419168, 2013). "It has been well established that breast cancer stem cells are characterized by CD44+CD24- phenotype, expression of Sca1 with high rates of tumorigenicity, in vivo." (PMID 24324806, 2013). "Further, activated Jak-STAT signalling is essential for the survival of CD44+/CD24-/low stem-like breast cancer cells and was shown to play an important role during mammosphere formation." (PMID 24229464, 2013). "Since CD44+CD24- breast cancer cells have been suggested to be cancer stem-like cells which also express the stem cell marker Sca1, we sought to determine the stemness capacity of the sorted cells." (PMID 24324806, 2013). "The breast cancer stem cell signature was generated by combining two subpopulations of 36 breast tumors sorted for CD44+/CD24-/low markers and the cells that were able to form mammospheres on low-attachment plates." (PMID 24008095, 2013). "Breast cancers, for instance, are classified into several subtypes, such as luminal, basal, and HER2+, but the well-known CD44+CD24− phenotype is closely associated with the basal type, and the HER2+-type CSCs show an ALDH+ phenotype." (PMID 23626764, 2013). "As biomarkers, CD44+/CD24-/low breast cells have been shown to have tumor-initiating properties in breast cancer, show enhanced invasive properties, and are more likely to become resistant to radiation therapy." (PMID 24167614, 2013). "Flow cytometry with CD44 and CD24 markers was used to sort breast cancer MCF7 cells for scanning electron microscopy (SEM), tumor cell invasion assay, and nude mouse xenograft assay." (PMID 23799994, 2013). "The ALDH+/CD44+/CD24− subpopulation of MDA-MB-231 and SUM159 breast cancer cells expressed higher levels of P-STAT3 compared to the un-separated or ALDH−/CD44+/CD24+ subpopulations." (PMID 24376586, 2013). "This study investigated CD44 and CD24 cell surface markers as breast cancer CSC markers in vitro and in vivo." (PMID 23799994, 2013).
breast cancer (continued). "The CD44+CD24– cell population is capable of self-renewal and generating tumors resembling breast cancer." (PMID 24331293, 2013). "For example, CD44+CD24− indicates breast cancer stem cells, whereas a pancreatic cancer stem cell phenotype is CD44+CD24+, and CD44+CD117+ is an ovarian cancer stem cell phenotype." (PMID 23626764, 2013). "In a series of colon and breast cancer cell lines, we found that CD24 activates Src, and induces the activation of c-Jun and expression of c-Jun and c-Fos." (PMID 23533633, 2013). "The CD44+/CD24- phenotype can be detected by immunohistochemistry and is related to the most aggressive tumor grades in canine mammary neoplasms." (PMID 24119896, 2013). "Using cell surface markers Al-Hajj and colleagues found that CD44+CD24−/low Lin− cells from breast cancer patients were significantly enriched for tumor forming ability in NOD/SCID mice compared with CD44+CD24+ Lin− cells." (PMID 23986719, 2013). "Breast cancer stem cells can be identified by a CD44(+) CD24(-/low) phenotype that augments mammosphere formation in vitro and exhibit increased resistance to chemo- and radiotherapy." (PMID 24392029, 2013). "Ectopic expression of CD24 in breast cancer cells has been shown to result in increased proliferation, as well as cell motility and invasion and the expression of CD24 in breast carcinomas has been associated with poor prognosis." (PMID 23785296, 2013). "Unfortunately, there is a paucity of data regarding the prevalence of the CD44/CD24 phenotype as a biomarker in breast tumor tissues and in relation to tumor clinicopathology among African-American and Hispanic women with breast cancer." (PMID 24167614, 2013). "Breast cancer cells that express the cell surface molecule CD44 (CD44+) but lack or have low expression of CD24 (CD24−) have been shown to have cancer stem cell properties." (PMID 24376586, 2013). "This is consistent with a recent report showing that the CD44+CD24- phenotype contributes to breast cancer relapse." (PMID 24324806, 2013). "Stem-like cells with tumour initiating capabilities have been found to be enriched in the CD44+/CD24-/low sub-population of basal breast carcinoma cells." (PMID 24229464, 2013). "In a review of previous studies, Clarke proposed that ER–, PR–, and CD44+ CD24–/low cells in breast cancer have the same characteristic of tumorigenic breast cancer stem cells." (PMID 23554768, 2012). "For breast cancer, it has been proposed that the subpopulation cells of CD44high/CD24-/low have cancer stem cell properties." (PMID 22309939, 2012). "It is also reported that hypoxia enriches the CD44+/CD24- breast cancer stem-like cells and CD44+ murine mesenchymal stem cells." (PMID 22642602, 2012). "Recently, it has been reported that disseminated breast cancer cells in human bone marrow are largely CD44+/CD24-, corresponding to EMT CSCs." (PMID 22934288, 2012). "ALDEFLUOR-positive CD44+CD24− Lin− breast cancer cells are a small and highly tumorigenic population, putatively enriched with stem cells." (PMID 22253899, 2012). "In breast cancer, several subpopulations, such as CD44high/CD24-/low, CD133/PROM/prominin, and ALDEFLUOR+, have been shown to contain highly enriched cancer stem cells." (PMID 22309939, 2012). "As researchers are able to isolate ESA+ CD44+CD24-/low LIN- cells from breast cancer tissues, more and more studies on BCSCs have appeared, particularly on CD44+CD24-/low cell’s clinical correlation." (PMID 23046710, 2012). "In this study, we examined the mechanism of tamoxifen resistance of CD44+CD24–/low breast cancer stem cells in vitro." (PMID 23554768, 2012). "Breast cancer stem cells, identified on the basis of CD44+CD24-/low expression, are associated with metastases and drug resistance." (PMID 23046710, 2012).
breast cancer (continued). "It has been shown that CD24 is a marker of tumor aggressiveness and that the expression of CD24 promotes breast cancer development." (PMID 23300877, 2012). "It is therefore important to investigate the proportion of CD44+CD24-/low breast cancer stem cells for the diagnosis of metastases in axillary nodes." (PMID 23046710, 2012). "In breast cancer, the CD24−/low/CD44+ marker combination has been shown to identify in vivo tumorigenic cell subpopulations, although the percentage of the subfraction did not correlate with the in vivo tumorigenicity." (PMID 23042145, 2012). "Upon isolation for breast cancer initiating CD44+CD24 −/low cells by employing magnetic activated cell sorting, we observed the kinetics of metformin-induced killing drastically varied among CSC and non-CSC subpopulations." (PMID 22565037, 2012). "A high percentage of BCSCs enriched with CD44+CD24-/low phenotype was found harbored in basal-like tumors and the phenotype was observed in ‘triple-negative’ breast cancer that responded poorly to chemotherapy." (PMID 23046710, 2012). "It has previously been reported that human breast cancer stem cells often have an EpCAM+CD44+CD24-/low phenotype." (PMID 23088371, 2012). "Independently, both CD44+ and CD24+ breast cancer cell populations have been shown to be involved in the metastatic process." (PMID 24212798, 2011). "For example, CD24 marks normal mammary stem cells but in combination with other cell surface markers, CD24-negative breast cancer cells are those with greatest tumour-initiating potential." (PMID 21934687, 2011). "The phenotype of CD44+/CD24- in breast cancer cells exhibits a higher potential compared to other phenotypes of breast cancer cell lines, however, this is not sufficient evidence to elucidate the relationship with pulmonary metastasis." (PMID 21749678, 2011). "We characterised the putative CSC-rich breast cancer by assessing the relationship between CD44/CD24 or ALDH1 expression in pre-chemotherapy tissue and clinicopathologic parameters." (PMID 21559013, 2011). "Our study aims to investigate the prognostic impact of CD44+CD24-/low immunoexpression in breast cancer." (PMID 21824412, 2011). "The interest for CD44 was reinforced by the finding that tumorigenicity of breast cancer cells was limited to a putative CSC subpopulation with CD44+/CD24-/low expression." (PMID 21957977, 2011). "The phenomenon of reversal of differentiation was not only exhibited with the altered expression of CD44/CD24 surface markers during culture but was also noticed in altered expression of ABCG2 in breast cancer cells." (PMID 21935375, 2011). "We isolated a breast cancer cell population (CD44+CD24- cells) from primary cultures of malignant breast tumors." (PMID 22152097, 2011). "An association with survival has been demonstrated by one study and gene signatures derived from CD44+ primary breast cancer cells and CD44+CD24- breast cancer cells (from xenografts or pleural effusions) have also been shown to correlate with outcome." (PMID 22112299, 2011). "Using a mammosphere culture technique, MCF7 mammosphere cells are found to enrich breast cancer stem-like cells expressing CD44+CD24-." (PMID 20569497, 2010). "Progressive genome modulation in the CD44+/CD24-/low subpopulation of the breast cancer cell line MDA-MB-468 leads to different coexisting subclones." (PMID 20199686, 2010). "Cancer cells that display the cell surface marker profile of CD44+/CD24-/Lineage- were the first described tumorigenic progenitor cell types for breast cancer." (PMID 20691079, 2010). "Phillips and colleagues also demonstrated the radioresistance of putative breast cancer stem/progenitor cells by comparing the radiosensitivity of cells derived from the CD44+/CD24-subpopulation of MCF-7 cell line grown as spheres vs. monolayers." (PMID 20615238, 2010). "For instance, mammosphere cells were found to enrich breast cancer stem-like cells with the phenotype of CD44+CD24-." (PMID 20569497, 2010).
breast cancer (continued). "In our model, initial immunohistochemistry revealed a greater presence of CD24-positive cells in both mammary tumors and pre-neoplastic mammary glands of MMTV-Wnt/ILK mice compared with the same tissue type in MMTV-Wnt mice (data not shown)." (PMID 20565980, 2010). "Breast cancer cells with CD44+/CD24- cell surface marker expression profile are proposed as cancer stem cells (CSCs)." (PMID 20691079, 2010). "The discovery of the CD44/CD24 phenotype and its relation with unfavorable prognosis in TN breast cancer disease also makes CD44 targeting an attractive therapeutic alternative." (PMID 21050424, 2010). "Several breast cancer cell lines were sorted with CD24 and CD44, known markers for enrichment of breast cancer TICs." (PMID 19997106, 2010). "Far beyond these genetic properties MDA-MB-468 CD44+/CD24-/LOW is a valuable model for studies in breast cancer progression because it is likely to represent a basal-like/stemness cell phenotype of breast cancer." (PMID 20199686, 2010). "Previous studies in both breast cancer cells and tissues have shown that breast cancer stem cells are cells with an ESA+CD44+CD24-/low phenotype." (PMID 21192833, 2010). "In reduction mammoplasty tissues, EpCAM+/CD24-/CD49f+ cells exhibited a basal cytokeratin phenotype while breast cancer cell lines with a basal-like phenotype also contained a unique population of EpCAM+/CD24-/CD49f+ cells." (PMID 20964822, 2010). "In contrast, cytotoxic chemotherapies including Dox increased the proportion of CD44/CD24- breast cancer cells and mammosphere-forming activity associated with a significant antitumor activity in HER2-negative breast cancers." (PMID 20959018, 2010). "Treatment of breast cancer cells with metformin led to a reduced CD44-high/CD24-low population, decreasing the ability of breast cancer stem cells to form mammospheres." (PMID 24281219, 2010). "Paired breast cancer core biopsies obtained from patients with primary breast cancer before and after 12 weeks of chemotherapy found that chemotherapy caused a 3-fold increase in the CD44+/CD24-/low breast CSC population." (PMID 20979639, 2010). "Breast cancer stem cells (BCSCs) have been recently identified in breast carcinoma as CD44+CD24- cells, which exclusively retain tumorigenic activity and display stem cell-like properties." (PMID 20569497, 2010). "A broad range of the egfr gene copy numbers leading to different EGFR expression levels can be found simultaneously under normal cell culture conditions in the breast cancer cell line MDA-MB-468 CD44+/CD24-/LOW." (PMID 20199686, 2010). "The basal-like/stemness type breast cancer cell line subpopulation MDA-MB-468 CD44high/CD24-/low, carrying high egfr amplifications, was chosen as a model system in this study." (PMID 20199686, 2010). "The expression profiles of stem-like cells from normal and neoplastic breast tissue were highly similar, and both expressed numerous stem cell markers, whereas both normal and breast cancer CD24+/CD44+/− cells had features of luminal differentiation." (PMID 24281098, 2010). "Breast carcinomas have been reported to contain a subpopulation of CD44+/CD24– tumor cells with stem-cell-like properties." (PMID 21050424, 2010). "Recently, a small subset of Thy1+/CD24+ cells purified from MMTV-Wnt-1 mammary carcinomas has been found to behave like CSCs." (PMID 20730114, 2010). "In cell lines from mammary tumors Brca1 knockout mice, the expression of CD133 cells is associated with stem cell properties as well as CD44+/CD24-/low phenotype." (PMID 19555472, 2009). "Since then, the CD44/CD24 profile has been widely investigated in both primary tissues and established breast cancer cell lines." (PMID 19906290, 2009). "Of interest, certain expression levels of CD24 and CD44 are considered as breast cancer stem cell markers and a significant reduction of CD24 and CD44 surface markers is observed during HMEC aging." (PMID 19751512, 2009).